IL17A (interleukin 17A)
Diseases named in the same sentence as IL17A in open-access papers (continued):
Sharing a sentence is not in itself a finding about the gene and the disease.
psoriasis (continued). "miR-146 is also positively correlated with IL-17A levels in psoriasis and in RA disease severity, and is co-expressed with IL-17A in the PBMC and synovium in RA patients." (PMID 26236331, 2015). "More recently, inflammatory cells other than Th17 – in particular, neutrophils, a numerically important component of the infiltrate in active psoriasis – have also been suggested as sources of IL-17A 10,11." (PMID 25828362, 2015). "More recently, a transcriptome evaluation study also demonstrated high IL-17A serum levels in moderate-severe psoriasis patients." (PMID 26351408, 2015). "Imiquimod has been reported to elicit IL-17A and IL-23 levels in mouse skin, which are features of human psoriasis." (PMID 26355594, 2015). "Consistent with this, IL17A expression was significantly elevated in psoriasis lesions (FC = 2.74; n = 237 patients)." (PMID 25883770, 2015). "Our findings demonstrate that IL-17A, IL-22, and IL-6 serum concentrations were significantly higher in psoriasis patients than in the control group." (PMID 26351408, 2015). "Potentially, these mouse phenotypes will better recapitulate unique mechanistic features of psoriasis lesion development, which appear to involve aberrant KC maturation and activation of IL-17A-directed pathways." (PMID 26251673, 2015). "By blocking the pathogenic driver IL-17A, the fully human antibody AIN457 (Novartis Pharmaceutical, Basel, Switzerland) has been shown to interrupt inflammation in patients with RA, psoriasis, and NIU." (PMID 24868451, 2014). "Many of these pathways have been previously shown to be upregulated in psoriasis, such as Atherosclerosis Signaling, and Role of IL-17A in Psoriasis." (PMID 25369198, 2014). "IL-17A, a key mediator in psoriasis pathogenesis, has been shown to enhance the induction of cathelicidin by vitamin D3." (PMID 24901012, 2014). "Although psoriasis patients show marked clinical benefit of targeting IL-17A, the clinical response in RA and PsA has been limited and variable between patients." (PMID 25146432, 2014). "IL-17A, a crucial player in pathogenesis of psoriasis, is principal inducer of both proteins which acts synergistically with other propsoriatic cytokines to induce S100A7 and S100A15." (PMID 24901012, 2014). "With their suitable biophysical properties, Fynomer-Fc fusion proteins represent new drug candidates for the treatment of IL-17A mediated inflammatory conditions such as psoriasis, psoriatic arthritis, or rheumatoid arthritis." (PMID 24692552, 2014). "The genes identified in IL-17-treated RHE are likely relevant to the IL-17 effects in psoriasis, since ixekizumab (anti-IL-17A agent) strongly suppressed the “RHE” genes in psoriasis patients treated in vivo with this IL-17 antagonist." (PMID 24587313, 2014). "In the present study, we used IL-17A as target because it is a proinflammatory cytokine that has been implied in many autoimmune diseases such as rheumatoid arthritis, psoriasis, Crohn's disease, multiple sclerosis, and lupus erythematosus." (PMID 24692552, 2014). "We defined the in vivo correlations of the novel gene set induced by IL-17 in RHE by analyzing the results of a recent clinical trial in psoriasis patients with a potent IL-17A antagonist, ixekizumab." (PMID 24587313, 2014). "Here, we report that topical use of a curcumin gel formulation strongly inhibited imiquimod (IMQ)-induced psoriasis-like inflammation, the development of which was based on the IL-23/IL-17A axis." (PMID 23825622, 2013). "Recently, administration with monoclonal anti-IL-17A antibodies demonstrated efficacy for psoriasis, where IL-17A is thought to play a critical role." (PMID 23637915, 2013). "Secukinumab (AIN457) is a fully human anti-IL-17A IgG1κ monoclonal antibody (mAb), being studied in clinical trials in psoriasis, RA, Crohn's disease (CD), psoriatic arthritis (PsA), ankylosing spondylitis and MS." (PMID 23968496, 2013).
psoriasis (continued). "Investigators confirmed that IMQ-induced psoriasis-like inflammation is mediated by the IL-23/IL-17A axis." (PMID 23825622, 2013). "Recently it has been reported that IL-17A in combination with TNF-α synergistically induced many psoriasis-related immune response genes including several cytokines and chemokines as well as AMP such as psoriasin and hBD-2." (PMID 23555696, 2013). "A functional role for the IL-23/IL-17A axis in the pathogenesis of psoriasis was suggested recently." (PMID 23825622, 2013). "Although the pathogenesis of psoriasis is not fully understood, there is growing evidence to indicate that the interleukin-23 (IL-23)/IL-17A cytokine axis plays a critical role in the disease development." (PMID 23825622, 2013). "Ixekizumab (LY2439821), a humanized IgG4 anti-IL17A mAb has showed efficacy in phases I and II in RA and psoriasis, respectively, and is currently being studied in RA, PsA and psoriasis." (PMID 23968496, 2013). "In cultured KCs, for example, stimulation with IL-17A leads to induction of β-defensins and pro-inflammatory S100 proteins, and such genes are consistently increased in psoriasis lesions." (PMID 23915137, 2013). "Recent studies have shown that IL-1 signaling represents a key step in IL-17A-mediated autoimmune diseases, including psoriasis." (PMID 23825622, 2013). "In psoriasis, IL-23 is produced at high levels by DCs and keratinocytes, and this cytokine stimulates Th17 cells to produce IL-17A and IL-22." (PMID 23956763, 2013). "In contrast, only two pathways (‘Interferon Signaling’ and ‘Role of IL-17A in Psoriasis’) related to inflammatory response were recognized in PHKs." (PMID 23702334, 2013). "It is on that basis, we discovered that curcumin can suppress inflammation in IMQ-induced psoriasis-like mice model and decrease the cytokines production, such as IL-17A, IL-17F, IL-22, IL-1β and TNF-α." (PMID 23825622, 2013). "Some success was also reported with anti-IL-17A and anti-IL-22 agents in animal models of psoriasis." (PMID 24151518, 2013). "The interleukin-23 (IL-23)/IL-17A cytokine axis plays a critical role in the pathogenesis of psoriasis." (PMID 23825622, 2013). "The top two enriched pathways were the role of IL-17A in psoriasis pathway and the complement system pathway." (PMID 24244515, 2013). "We found that injecting anti-IL-9 antibody into K5.hTGF-β1 transgenic mice not only diminished the psoriasis-like morphological changes, including cellular infiltration and neo-vascularization of the skin, but also reduced expression of IL-17A." (PMID 23335955, 2013). "Secukinumab is another anti-IL-17A monoclonal antibody that has demonstrated efficacy for induction and maintenance treatment in patients with moderate to severe psoriasis." (PMID 24276125, 2013). "Recently, Th17 cells have been suggested to be involved in the pathogenesis of psoriasis synthesizing IL-17A, IL-17F, and IL-22." (PMID 23213332, 2012). "The top canonical signalling pathways were “Role of IL-17A in Psoriasis”, “Hepatic fibrosis” and “NF-kB signalling”." (PMID 22880105, 2012). "Whatever the case, IL-17A expression in lesional AD is almost unchanged when compared to normal skin, whereas it is increased in psoriasis (unpublished data)." (PMID 23193414, 2012). "In fact, IL-17A, IL-22, and IL-23 are elevated in psoriatic skin, and IL-17A together with TNFα induces the expression of genes involved in psoriasis in human keratinocytes." (PMID 22229105, 2012). "In particular, γδ T cells which express IL-17A in response to IL-1α/β play an important role in driving neutrophilia and dermal inflammation in psoriasis in both mouse models and human patients." (PMID 22891068, 2012). "Our data is consistent with recent reports in psoriasis skin biopsies showing similar IL-17A expression patterns." (PMID 21887369, 2011). "A recent report found that IL-17A augmented vitamin D3-mediated CAMP production in keratinocytes during psoriasis." (PMID 22174673, 2011).
psoriasis (continued). "Although recent studies indicate a crucial role for IL-17A and IL-22 producing T cells in the pathogenesis of psoriasis, limited information is available on their frequency and heterogeneity and their distribution in skin in situ." (PMID 21124836, 2010). "Several observations support the involvement of the IL-23/IL-17A pathway in the pathogenesis of psoriasis." (PMID 21124836, 2010). "The understanding of the crucial role of IL-17A in skin inflammation in psoriasis is rapidly evolving." (PMID 19623255, 2009). "Psoriasis and psoriatic arthritis (PsA) are chronic, immune-mediated inflammatory diseases driven predominantly by dysregulation of the IL-23/Th17 axis, with central contributions from IL-23, IL-17A/F, and TNF-α." (PMID 41596733, 2026). "However, in psoriasis, IL-17A and IL-17F exhibit distinct gene expression profiles and regulatory mechanisms in Th17 cells." (PMID 40536951, 2026). "Although biologics have markedly improved psoriasis symptoms, they may occasionally trigger paradoxical inflammatory reactions, particularly with IL-17A or TNF-α inhibitors." (PMID 42079624, 2026). "With a BL-responsive shell, Apt-GA+Cur@μmS released curcumin (Cur) to assist BL to improve the preventative and therapeutic effects in the psoriasis relapse murine model, as evidenced by the psoriasis area and severity index, histology, splenic index, and dorsal IL-17A level." (PMID 41482938, 2026). "In addition to targeting IL-17A, newly available simultaneous targeting of IL-17F appears to show enhanced efficacy compared to inhibition of IL-17A alone in psoriasis." (PMID 41322402, 2025). "Pro-inflammatory cytokines like TNF-α, IL-17A/F, and IL-22 play a major role in psoriasis." (PMID 40507817, 2025). "Furthermore, we investigated the relationship between Wnt5a and IL-17A in psoriasis to provide a novel theoretical basis for the clinical application of TP and new targets for psoriasis treatment." (PMID 40365308, 2025). "In this study, in order to explore the relationship between PGGT1B deficiency and inflammation in psoriasis, we also detected the mRNA and cytokine expressions of inflammatory factors IL-1β, IL-6, TNF-α, IL-17A, and IL-10 in the most serious stage of skin injury in mice." (PMID 40430037, 2025). "The combination of TNF‐α and IL‐17A has a pivotal role in the inflammatory cascade of psoriatic keratinocytes, where they activate the NF‐κB signaling pathway, leading to the overexpression of downstream genes, including Arg1 and psoriasis‐related genes." (PMID 39665264, 2025). "Moreover, the CARIMA study demonstrated that secukinumab, an IL-17A inhibitor, improved endothelial function in patients with psoriasis, suggesting vascular benefit through modulation of endothelial inflammation." (PMID 40727466, 2025). "Even extracardiac diseases such as psoriasis can provoke myocarditis through systemic interleukin-17A-driven inflammation and cross-reactive autoantibodies, demonstrating that chronic skin immune activation may affect the heart." (PMID 40821166, 2025). "Likewise, anti-IL-17A antibodies such as Secukinumab and Ixekizumab have been observed to improve evaluated anxiety and depression in psoriasis." (PMID 40077004, 2025). "Given the highly unmet needs in patients with psoriasis involving difficult-to-treat areas and the promising profile of bimekizumab as a dual IL-17A/IL-17F inhibitor, our study aims to assess the real-world effectiveness and safety of this drug in this specific subpopulation." (PMID 41156280, 2025). "IL-17A and IL-17F, members of the interleukin-17 family, are pivotal in psoriasis pathogenesis." (PMID 40948748, 2025). "This connection may be driven by inflammation involving the cytokine IL-17A, which is elevated in both psoriasis and ASD." (PMID 40497203, 2025). "Notably, the IL-17A levels were even higher than those observed in classic psoriasis, suggesting a pronounced Th17 shift triggered by dupilumab." (PMID 41517378, 2025).
psoriasis (continued). "Therefore, in this study, we aimed to evaluate the therapeutic potential of the anti‐IL17A aptamer M2 (17 nucleotides) conjugated with AuNPs in the imiquimod‐induced C57BL/6 mouse model of psoriasis." (PMID 41477217, 2025). "Later, IL-17A was also identified as a crucial player in the innate-like immune response against extracellular bacterial and fungal infections, and as a key component in autoimmune diseases including psoriasis, multiple sclerosis, and ankylosing spondylitis." (PMID 40469524, 2025). "Thus, TP exerted a regulatory effect on the IL23/Th17 axis and an inhibitory effect on IL-17A production and secretion during psoriasis treatment." (PMID 40365308, 2025). "However, in diseases linked to MHC-I genes, including psoriasis, PsA, and axSpA, it is likely that tissue-resident memory (TRM) CD8+ T cells are key producers of both IL-17A and IL-17F; future studies should aim to address this." (PMID 41322402, 2025). "IL‐17A has been identified as one of the key disease drivers of psoriasis." (PMID 40970551, 2025). "Simultaneous blockade of both cytokines, which are key mediators of the Th17-dependent inflammatory axis, may lead to more effective suppression of inflammation than neutralising IL-17A alone in patients with moderate to severe psoriasis." (PMID 41002407, 2025). "A clinical study has demonstrated that psoriasis patients treated with secukinumab (an IL-17A antibody) for 12 weeks exhibited a reversal of plaque histopathology, along with a significant reduction in the levels of upstream cytokines IL-23 and IL-17A." (PMID 41142781, 2025). "Moreover, vitamin D analogues and calcitriol have exhibited hepatoprotective effects and anti-psoriasis activity by downregulating IL-17A secretion." (PMID 40299638, 2025). "Measures of periodontitis distance between the cemento‐enamel junction and alveolar bone crest (CEJ–ABC) and number of osteoclasts and psoriasis (epidermal thickness and infiltrate cells (per 0.03mm2)) severity, as well as systemic inflammation (IL‐6, IL‐17A and TNF‐α) were collected." (PMID 40277096, 2025). "Dysregulation of the IL-23/Th17 pathway has been implicated in several autoimmune diseases, including SLE/LN, and inhibition of IL-23 and IL-17A with guselkumab and secukinumab, respectively, has demonstrated efficacy in improving the signs and symptoms of psoriasis and PsA." (PMID 39673415, 2025). "IL-17A plays an important role in the pathology of psoriasis and psoriatic arthritis (PsA)." (PMID 39919800, 2025). "BIRC5 is a gene that encodes a protein called survivin, and its abnormal expression in psoriasis may be related to the regulation of cell apoptosis and survival in the IL-17a and IL-23 pathways." (PMID 40557155, 2025). "Together, these data demonstrated an inner link between Arg1 and innate immune cells (DCs) and adaptive immune cells (Th17), which might be IL‐17A secreted by DC/Th17A axis driving the Arg1 upregulation in psoriasis." (PMID 39665264, 2025). "Sonelokimab (M1095) was used against Psoriasis by targeting interleukin-17A/F." (PMID 41009364, 2025). "In order to explore the relationship between PGGT1B deficiency and inflammation in psoriasis, we measured the mRNA and cytokine expressions of inflammatory factors IL-1β, IL-6, TNF-α, IL-17A, and IL-10 in the most serious stage of skin injury in mice using Luminex and qRT-PCR." (PMID 40430037, 2025). "Furthermore, cytokines like IL-17A and IL-23 are also key players in psoriasis, and therapeutic interventions targeting these cytokines and their receptors such as ustekinumab, guselkumab, tildrakizumab, and risankizumab presently provide relief to patients." (PMID 39997616, 2025). "Previous studies have demonstrated that psoriasis patients exhibit an elevated risk of developing IBD, which may be attributed to the protective role of IL-17A in intestinal homeostasis." (PMID 41560729, 2025).
psoriasis (continued). "Additionally, IL-17a, important in the pathophysiology of psoriasis, has been found to suppress autophagy by preventing autophagosome development." (PMID 40565008, 2025). "Moreover, daphnetin has been revealed to significantly alleviate erythema, scaling, epidermal thickness, and inflammatory cell infiltration in psoriasis-like mice by attenuating upregulation of IL-6, IL-23A, and IL-17A in the skin lesions of mice." (PMID 41462398, 2025). "Estradiol can suppress IL-17A production from neutrophils and macrophages, which express estrogen receptors, resulting in psoriasis clinical phenotypes by sex-dependent differences, indicating that sex differences make the side effect risk of IL-23 inhibitors higher in females." (PMID 40332543, 2025). "Finally, in vitro experiments were conducted using XYJDY-containing serum to intervene in the IL-17A-induced HaCaT cell psoriasis-like inflammation model, confirming the impact of XYJDY on AKR1B10 expression." (PMID 40735022, 2025). "In support of this, CAP significantly reduced inflammatory cytokines such as IL‐17A, IL‐23A, IL‐24, IL‐1β, and TNFα in psoriasis cells and modulated critical factors in the MAPK pathway in vitro, and led to substantial improvements in factors such as skin thickness, erythema and scaling in vivo." (PMID 40989573, 2025). "IL-17-A, IL-17F, and IL-17-A/F are primarily involved in the development of psoriasis." (PMID 40243580, 2025). "Moreover, treatment with a cocktail of cytokines (IL-17A, IFNγ, TNFα) to induce a psoriasis-like phenotype in keratinocytes, increased ALOX15B RNA and protein expression." (PMID 39843435, 2025). "Whilst the head-to-head data in psoriasis has established superior efficacy of dual IL-17A and IL-17F in the skin compared to other biologic disease modifying anti-rheumatic drugs (bDMARDS) such as adalimumab and secukinumab, similar efficacy was observed at the joint compared to anti-TNF." (PMID 41322402, 2025). "In psoriasis patients, IL-17A levels are notably increased at skin lesions and nearby tissues, correlating positively with lesion severity and KCs are the primary targets of IL-17A." (PMID 40303401, 2025). "Since IL-23 is critical for the development of pathogenic IL-17 A-producing γδ T cells, we examined the expression of IL-23p19, a component of IL-23, in the skin of mPGES-1−/− mice and WT mice during IMQ-induced psoriasis." (PMID 40481552, 2025). "These cases emphasize the importance of a thorough history of pemphigoid and BP180 autoantibody status in psoriasis patients before initiating IL-17A inhibitor therapy, urging caution among clinicians when considering these biologics for patients with a pemphigoid history." (PMID 40422272, 2025). "Notably, Il23 and Il17a expression remained unchanged either by diet or imiquimod treatment, suggesting that adipose tissue inflammation in obese mice with psoriasis proceeds independently of direct activation of the IL-23/IL-17 axis." (PMID 40860129, 2025). "Among them, IL-17A and IL-23 are the key factors in the pathogenesis of psoriasis." (PMID 41142781, 2025). "Many inhibitors developed against psoriatic cytokines have shown promising results; for example, secukinumab and ixekizumab targeting IL-17A and brodalumab targeting the IL-17A receptor have been approved by the Food and Drug Administration for treating moderate-to-severe psoriasis." (PMID 40365308, 2025). "In psoriasis patients, FOXP3+ Tregs may undergo differentiation into IL-17A-producing cells, indicating a loss of their regulatory function." (PMID 40584971, 2025). "Additionally, a BTK inhibitor was discovered to decrease imiquimod (IMQ)-induced psoriasis-like inflammation by modulating IL-23/IL-17A in innate immune cells, establishing a physiological link involving immune control and symptom alleviation." (PMID 40667480, 2025). "Moreover, IL-17A principally drives the expression of four key cytokines: IL-36, IL-17C, IL-20, and IL-19, each possessing distinct functions in psoriasis." (PMID 40303401, 2025).